CCL2 (C-C motif chemokine ligand 2)
Diseases named in the same sentence as CCL2 in open-access papers (continued):
Sharing a sentence is not in itself a finding about the gene and the disease.
AIDS (22 papers, 2008 to 2025). A syndrome resulting from the acquired deficiency of cellular immunity caused by the human immunodeficiency virus (HIV). "Another critical question that warrants further investigation is whether HIV-2 loses its ability to inhibit CCL2 production later in the disease process, thereby contributing to the progression to AIDS." (PMID 38005838, 2023). "Thus, chronic diarrhea and/or weight loss in African AIDS patients is associated with increased levels of macrophage related cytokines (TNF-α and IL-1β) and chemokines (CCL2) compared to HIV-negative healthy controls." (PMID 26475133, 2015). "This signal transduction pathway is required for expression of CCL2, a chemokine playing an important role in AIDS pathogenesis by recruiting CCR2 positive cells as new targets for infection, contributing to immune activation and enhancing viral replication both in macrophages and T lymphocytes." (PMID 23555755, 2013). "Plasma levels of LPS, sCD14, IL-6, and CCL2 were higher in AIDS compared to uninfected subjects." (PMID 18575590, 2008). "In addition, pre-treatment plasma levels of biomarkers of immune activation/inflammation (sTNF-RII, sCD25), microbial translocation (sCD14), and/or macrophage activation (BAFF/BLyS and CCL2/MCP-1) are associated with overall survival and progression-free survival of AIDS-NHL patients." (PMID 39324141, 2024). "According to our results, most HIV-patients had low CXCL8 and CCL2 levels, a finding probably related to their HIV/AIDS status." (PMID 34829225, 2021). "Ex vivo studies of total MMC (containing CD14+ macrophages) isolated from the colon of AIDS patients indicated that these cells secreted increased levels of TNF-α, IL-6, CCL2 and CXCL10 compared to HIV-negative controls." (PMID 26475133, 2015). "IL-18, CCL2, TRAF6 and IL-12Rβ1 were upregulated in both AIDS and IBD patients compared to controls." (PMID 26475133, 2015). "Additionally, CCL2 is major mediator of pain, and chronic pain is a common burden in people living with HIV/AIDS." (PMID 31681324, 2019). "The HIV and SIV Nef protein, a progression factor in AIDS pathology, can be transferred by microvesicles including exosomes and tunneling nanotubes (TNT) within the host even to uninfected cells, and Nef can induce CCL2 expression." (PMID 31681324, 2019). "We detected higher levels of IL-2R, CXCL9, CXCL10, CCL2, and IL-6 (p = 0.001, 0.0003, 0.0002, 0.017, and 0.0005, respectively) in plasma of AIDS patients compared to healthy uninfected controls (data not shown)." (PMID 21125014, 2010). "Moreover, cytokines such as M-CSF, IFN-γ, and CCL2, which are increased in blood and other tissues during HIV/AIDS disease progression, can enhance monocyte sensitivity to LPS stimulation." (PMID 18575590, 2008). "In the absence of LPS, unstimulated total MMC from AIDS patients secreted significantly higher levels of macrophage related pro-inflammatory cytokines (TNF-α and IL-6) and chemokines (CCL2, CXCL10) compared to the MMC isolated from healthy controls." (PMID 26475133, 2015).
leprosy (22 papers, 2012 to 2025). Leprosy is a chronic infectious disease affecting primarily the skin and peripheral nervous system. "Several studies report that the varying levels of chemokines such as CCL2 can influence the predisposition and severity of leprosy." (PMID 36142557, 2022). "In a final set of experiments we found that genetic risk factors of leprosy located in the PARK2 promoter region were significantly correlated with M. leprae sonicate triggered CCL2 and IL6 transcript levels in whole blood assays." (PMID 23350010, 2013). "Moreover, we demonstrate significant correlation of IL6 and CCL2 transcript levels in a whole blood assay with specific variants of PARK2 previously identified as leprosy risk factors." (PMID 23350010, 2013). "Our study shows that elevated expression of CCL2 in leprosy patients and this feature can be used to distinguish leprosy patients from non-leprosy controls." (PMID 34993156, 2021). "Samples from leprosy patients showed down-regulation of CCL2, CCL3, CCL4 (p<0.05), while IL1β and SOD2 were borderline significant (p<0.1), confirming a repression of these genes by M. leprae ex vivo, as was observed in vitro in THP-1." (PMID 23798993, 2013). "The elevated expression of CCL2 may indicate it is likely to be an inflammatory cytokine involved in the pathogenesis of leprosy." (PMID 34993156, 2021). "Here, we could speculate that a prominent triggering of STING signaling and high expression of type I IFN and CCL2 may contribute to the attraction of immune cells and enhancement of inflammatory response during leprosy reaction." (PMID 30143000, 2018). "Finally, several genes clustered in the 17q11–q21 region, such as chemokines CCL2, CCL3, CCL4, CCL5 and CCL7, were also linked to leprosy." (PMID 23798993, 2013). "However, the most interesting aspect of these experiments was that the same alleles in the same SNPs impacted both CCL2 and IL6 transcript levels and susceptibility to leprosy." (PMID 23350010, 2013). "Moreover, we found decreased expression of NCF1C among leprosy patients could distinguish leprosy from HHCs, whereas higher expression of CCL2 among MB than PB could distinguish different leprosy patients." (PMID 34993156, 2021). "In addition, higher expression of CCL2 among MB than PB leprosy patients could distinguish different leprosy patients." (PMID 34993156, 2021). "Plasma levels of the chemokines CCL2, CCL3 and CCL11 can be detected in patients with leprosy lesions and remain unchanged after leprosy treatment." (PMID 38381878, 2024). "We found that a 5 gene signature set IL-8, CCL2/MCP-1, SERP, LINC00659 and FLJ10489 had a suitable performance in discriminating leprosy from ECs." (PMID 34993156, 2021). "In conclusion, among the 12 candidate host genes identified, a three gene signature IL-8, CCL2/MCP-1, and SERP showed the best performance in distinguishing leprosy patients from healthy controls." (PMID 34993156, 2021). "In sum, IL-8, CCL2, SERP, and NCF1C showed an excellent performance in distinguishing leprosy patients from healthy controls." (PMID 34993156, 2021). "In addition, LOC34487, LOC101928143, CCL2, and NCF1C had the potential to distinguish MB and PB leprosy patients from HHCs." (PMID 34993156, 2021). "Second, the molecular mechanisms by which host biomarkers, such as IL-8, CCL2 regulate immune response and leprosy pathogenesis are not clear and require further clarification." (PMID 34993156, 2021). "In this study, using a different approach of transcriptomic analysis of PBMCs, we found that IL-8, CCL2, and SERP could not only discriminate between leprosy patients and ECs but also between MB and PB leprosy patients and ECs." (PMID 34993156, 2021). "There was no CXCL10 and CCL2 expression found in the nerve sections of non-leprosy group." (PMID 38590701, 2024).
leprosy (continued). "These candidate genes were then validated using PBMCs of MB and PB leprosy patients, HHCs, and ECs in a separate validation cohort, and we found that elevated expression of a 5-gene set IL-8, CCL2/MCP-1, SERP, LINC00659 and FLJ10489 could discriminate leprosy patients from ECs." (PMID 34993156, 2021). "Similarly, a Brazilian study analysing 90 immune related genes, showed that CCL2 had the highest fold change in expression levels between leprosy patients with and without RR53 and increased CCL2 expression in RR patients has also been described in other studies." (PMID 31784594, 2019).
lymphoma (22 papers, 2009 to 2025). A malignant (clonal) proliferation of B- lymphocytes or T- lymphocytes which involves the lymph nodes, bone marrow and/or extranodal sites. "According to these observations, we found an increased production of CCL2 that we could associate with the increased presence of TAMs in the lymphomas of Ibtk+/- Eμ-myc compared to Ibtk+/+ Eμ-myc mice." (PMID 32019112, 2020). "We thus chose to inject C57BL/6 mice with the tumor cell line E.G7-OVA, a lymphoma cell line expressing the antigen ovalbumin as well as similar levels of CCL2 compared with TRAMP metastatic lymph nodes." (PMID 27177227, 2016). "Of interest, the ability of MSC cultures of secreting high levels of angiogenic cytokines, such as VEGF, IL-8, angiogenin and CCL2, was significantly (p<0.01) enhanced by the concomitant presence of lymphoma cells." (PMID 20585401, 2010). "We sought to assess whether the increased production of CCL2 in Ibtk+/- Eμ-myc lymphomas could affect the presence of TAMs." (PMID 32019112, 2020). "In particular, we observed enhanced tumor angiogenesis, increasing pro-angiogenic and lymphangiogenic factors, such as VEGF, MMP-9, CCL2, and VEGFD, and a significant recruitment of tumor-associated macrophages in lymphomas of Ibtk+/-Eμ-myc compared to Ibtk+/+Eμ-myc mice." (PMID 32019112, 2020). "A historical discovery of the role of chemoattractant GPCR/ligand interactions in promoting cancer metastasis was reported in 1998, in which the chemokine CCL2 (MCP-1) was shown to mediate kidney specific metastasis of a subpopulation of a murine experimental lymphoma." (PMID 25110692, 2014). "Mutation or loss of function may lead to abnormal activation of the notch signaling pathway, which further increases the expression of CCL2 and CSF1 and promotes the transformation of tumor-associated macrophages (TAM) to M2 phenotype, thus promoting lymphoma cell proliferation." (PMID 40589747, 2025). "Thus, the increased lymphoma vascularization of Ibtk+/- Eμ-myc mice could be a consequence of the upregulated CCL2/TAMs/VEGF network." (PMID 32019112, 2020). "Consequently, we confirmed the presence of CCL2 in lymphoma tissues by immunoblotting." (PMID 32019112, 2020). "In addition, our results indicate that M2 macrophages induced an enrichment in FL cells of cytokines and chemokines that may attract other immunes populations, reshaping the lymphoma niche, such as CCL2 and CCL3 and IL-8, which may facilitate the recruitment of monocytes and neutrophils." (PMID 33731849, 2021). "Other studies have demonstrated that CCL2 may be prognostic in dogs with IMHA, lymphoma, and babesiosis." (PMID 31316998, 2019).
meningitis (21 papers, 2006 to 2025). A disorder characterized by acute inflammation of the meninges of the brain and/or spinal cord. "Intermediately, the EA ST28 strain MNCM43, which caused meningitis, induced a significant production of IL-1β, CCL2, and CCL3 only (p < 0.05)." (PMID 27409640, 2016). "have also found inflammatory markers elevated in the CSF during VZV-related meningitis, including interferon gamma, interleukins IL-6, IL-8, IL-10, IL-17F, IL-1RA, chemokines CXCL-9, CXCL-10, CCL-2 and G-CSF." (PMID 40416981, 2025). "Other cytokines known to be upregulated in the CSF during meningitis are CSF2 (GM-CSF), CCL2 (MCP-1), CCL4 (MIP-1β)." (PMID 34863201, 2021). "Subsequent RT-PCR analyses confirmed our assay results: CL-treated meningitis animals showed higher expression levels of CCL2 and CXCL2 (but not GFAP) compared to PBSL-treated mice." (PMID 40988032, 2025). "Therefore, the combination of significant pleocytosis with elevated levels of inflammatory mediators, such as IL-1β, CCL2, and CCL3, may differentiate modest procedure-related sterile meningitis from an active infection." (PMID 31262978, 2019). "While the functions of many induced cytokines in C. neoformans infection remain not known, clinical investigations have demonstrated that CCL2 and CCL3 are induced in meningitis-forming patients." (PMID 31329596, 2019). "The concentrations of the cytokines IFN-γ, IL-6 and TNF and the chemokine CCL2 were not significantly different between the WT and GKO meningitis animals, but a significantly lower concentration of IL-1β in the CSF was observed in the GKOs (p = 0.005)." (PMID 31700009, 2019). "Compared with controls with no meningitis at presentation, patients with TBM had significantly higher (P < .05) CSF concentrations of 28 of 32 mediators; only CCL2 and IL-17 levels were similar, and IL-18 and C5a had medians equal to 0 in both groups." (PMID 25107295, 2014).
Myocardial fibrosis (21 papers, 2013 to 2025). "In a left ventricular pressure overload model, CCL2-mediated macrophage recruitment induces myocardial fibrosis through a TGF-β-mediated process." (PMID 41208882, 2025). "In a left ventricular pressure overload model, CCL2-mediated macrophage aggregation acted on myocardial fibrosis via a TGF-β-mediated process." (PMID 36110847, 2022). "Moreover, activin-A, TNF-alpha, IL6, and MCP1/CCL2 secreted by EAT contributes to myocardial fibrosis." (PMID 34948944, 2021). "Neutralization of CCL2 inhibited macrophage aggregation, TGF-β induction, and fibroblast proliferation, while attenuating diastolic dysfunction and reducing myocardial fibrosis." (PMID 36110847, 2022). "Furthermore, the experimental results suggested that GZD could downregulate the expression levels of IL-6, IL-1β, CCL2, MMP-2, and MMP-9, thus inhibiting the inflammation and myocardial fibrosis in Dahl salt-sensitive rats." (PMID 33906674, 2021).
oral squamous cell carcinoma (21 papers, 2010 to 2026). "The CCL2/CCR2 signaling axis offers a new research direction for treating oral squamous cell carcinoma." (PMID 42038362, 2026). "Increasing KIF4A can promote the recruitment of macrophages toward oral squamous cell carcinoma cells and educate them to M2 polarized macrophages through regulating CCL2/CCR2." (PMID 33101367, 2020). "Many cancer types, including oral squamous cell carcinoma, exhibit constitutive expression of CCL2 and IL-6, whereas normal oral mucosal epithelial cells express lower levels of these cytokines and chemokines." (PMID 24213108, 2011). "Furthermore, higher expression of CCL2 in precancerous oral lesions and oral squamous cell carcinoma are often identified when compared with normal oral mucosa." (PMID 39727946, 2024). "Despite CCL2, several other cell migration-associated genes such as LCN2, ID-1, MDK, S100A9 significantly decreased after long-term exposure to oroxylin A. Moreover, oroxylin A inhibited oral squamous cell carcinoma metastasis in vivo." (PMID 32521759, 2020). "Moreover, long-term exposure to oroxylin A, a flavonoid extracted from Scutellaria radix, inhibited metastasis in oral squamous cell carcinoma cells by suppression of CCL2 and a decrease of its downstream targets, including p-ERK1/2, NFκB, MMP2, and MMP9." (PMID 32521759, 2020). "Upon downregulation of CCL2, miR-550a-3-5p inhibited M2 macrophage polarization, leading to suppression of migration, invasion, and EMT in HPV-positive oral squamous cell carcinoma." (PMID 35701841, 2022). "Oral squamous cell carcinoma can be robustly stimulated by poly(I:C) upregulating the expression of IL-6, TNFα, IL-8, vascular endothelial growth factor (VEGF), IL-1β, and monocyte chemoattractant protein 1 (MCP-1) (CCL2)." (PMID 34830032, 2021). "Similarly, in oral squamous cell carcinoma (OSCC), the silencing of gal-1 in CAF negatively affected cell migration and invasion by reducing the amount of monocyte chemotactic protein-1 (MCP-1/CCL2)." (PMID 29258258, 2017).
osteoporosis (21 papers, 2017 to 2025). A condition of reduced bone mass, with decreased cortical thickness and a decrease in the number and size of the trabeculae of cancellous bone (but normal chemical composition), resulting in increased fracture incidence. "Dysregulation of the CCL5/CCL5 ratio is associated with elevated serum levels of CCL2 in osteoporosis patients." (PMID 41416066, 2025). "Human studies correlating Ccr2 and Ccl2 gene variants with osteopenia and osteoporosis risk demonstrated the important role of the CCR2 pathway in the skeletal system." (PMID 37371471, 2023). "In osteoporosis, dysregulation of the CCL2/CCL5 ratio is associated with disease progression and may contribute to the pathophysiology of bone loss." (PMID 41416066, 2025). "In osteoporosis and other metabolic bone disorders, dysregulation of chemokine networks—particularly imbalances such as the CCL2/CCL5 ratio—has emerged as a critical factor driving disease progression and bone loss." (PMID 41416066, 2025). "In human studies, CCL2 and CCR2 gene variants were identified as potential risk factors for osteoporosis and osteopenia." (PMID 37457301, 2023). "Notably, Hu and colleagues observed an inverse correlation between CXCL1 and CCL2 in serum samples from 24 patients, suggesting that these cytokines may serve as potential novel predictors of early bone loss and be clinically relevant for the diagnosis and prevention of osteoporosis." (PMID 40723413, 2025). "Cytokines and chemokines such as TNF-α, CCL-2, IL-10, SERT (Serotonin Transporter) and Tph1 may be possible mediators between the GM and steroid deficiency-induced osteoporosis." (PMID 32484785, 2020). "Moreover, the secretion of chemokines, such as CCL2 and CCL3, underscores the inflammatory context associated with osteoporosis, which could further accelerate bone remodeling processes." (PMID 40564069, 2025). "Elevated circulating levels of CCL2, CCL3, CCL4, and CCL5 have been reported in patients with osteoporosis, suggesting that excessive chemokine signaling may enhance osteoclast recruitment and inflammatory bone resorption." (PMID 41416066, 2025).
pancreatic ductal adenocarcinoma (21 papers, 2013 to 2026). An infiltrating adenocarcinoma that arises from the epithelial cells of the pancreas. "Pancreatic ductal adenocarcinoma cells educate fibroblasts through the secretion of CCL2 and IL-8, leading to CAFs and similar metastasis-related fibroblasts." (PMID 33297571, 2020). "Inhibition of CCL2 improved radiation resistance using mice transplanted with pancreatic duct adenocarcinoma cell lines." (PMID 33297571, 2020). "Conversely, enhancer-driven C-C motif chemokine ligand 2 (CCL2) production in pancreatic ductal adenocarcinoma leads to the recruitment of TNF-α-positive macrophages and triggers the transition from a “classical” subtype to a more aggressive “basal-like” subtype." (PMID 40032852, 2025). "Moreover, PPARδ was found to dramatically accelerate pancreatic ductal adenocarcinoma development by activating the PPARδ-CCL2/CCR2 axis or the GOT2-PPARδ axis to drive immunosuppression through suppressing T cell-mediated anti-tumor immunity." (PMID 37572185, 2023). "Furthermore, ablative radiotherapy increased the production of tumour‐derived CCL2 in a pancreatic ductal adenocarcinoma model, and the increased CCL2 promoted the recruitment of Ly6C+CCR2+ monocytes in tumour sites, thereby accelerating tumour development." (PMID 34464477, 2021). "Radiotherapy leads to a significant increase in CCL2 production by pancreatic ductal adenocarcinoma cells and recruitment of TAMs, and neutralizing anti-CCL2 antibody selectively inhibits radiotherapy-dependent recruitment of TAMs and delays tumor growth in combination with radiotherapy." (PMID 33297571, 2020). "Furthermore, Snail can favor the recruitment of tumor-associated macrophages via CCL2 and 5 production in several cancer cell types and mast cells via SCF-1 release by pancreatic ductal adenocarcinoma cells." (PMID 30190790, 2018). "Overall, our findings are supported by a recent publication from Kalbasi et. al., showing an RT-specific increase in the production of CCL2 by tumor cells in pancreatic ductal adenocarcinoma models, and an increased efficacy of RT when this chemokine is depleted." (PMID 27852031, 2016). "In pancreatic ductal adenocarcinoma, HDAC5 could repress the suppressor of cytokine signaling 3 (SOCS3), a negative regulator of chemokine CCL2, contributing to elevated CCL2 and following recruitment of M2 macrophages." (PMID 37273004, 2023). "Some chemokines, such as CCL5 (RANTES), CXCL10 and CCL2 induced by TNFα, also have been reported to locally recruit both CAR T cells and endogenous T cells when combined with adenoviral OV and mesothelin-redirected CAR T cells in pancreatic ductal adenocarcinoma model." (PMID 36353540, 2022).